RNU6-800P (RNA, U6 small nuclear 800, pseudogene)
Gene: Small nuclear RNA gene on chromosome X (10,582,817 to 10,582,919, forward strand). Ensembl gene ENSG00000207202.
Homologues: Orthologues: chimpanzee U6 (97% identical), macaque U6 (96% identical), dog U6 (81% identical), rat LOC120093304 (77% identical). Paralogues in human: RNU6-1011P (89% identical), RNU6-1060P (88% identical), RNU6-1075P (88% identical), RNU6-1145P (88% identical), RNU6-116P (88% identical), RNU6-147P (88% identical), RNU6-338P (88% identical), RNU6-41P (88% identical), RNU6-44P (88% identical), RNU6-1201P (87% identical), RNU6-12P (87% identical), RNU6-1303P (87% identical), and 1287 more.